AKAP11 (A-kinase anchoring protein 11)
Description:
Binds to type II regulatory subunits of protein kinase A and anchors/targets them.
Synonyms: AKAP-11; PRKA11; AKAP220; KIAA0629; FLJ11304; DKFZp781I12161; PPP1R44
Tractability: Antibody: its Gene Ontology location is reachable by antibodies, with high confidence. PROTAC: ubiquitination databases record sites on it; its protein half-life has been measured.
Gene: Protein-coding gene on chromosome 13 (42,271,475 to 42,323,283, forward strand). Ensembl gene ENSG00000023516.
Subcellular location: Cytoplasm; Cytoplasm, cytoskeleton, microtubule organizing center, centrosome
Subcellular location (Human Protein Atlas): Cytosol; Nucleoli; Plasma membrane
Gene Ontology:
Molecular function: protein binding; protein kinase A binding; protein phosphatase 1 binding; protein kinase A regulatory subunit binding
Biological process: cell surface receptor protein serine/threonine kinase signaling pathway; intracellular protein localization; intracellular signal transduction
Cellular component: cytosol; cytoplasm; centrosome
Genetic constraint (gnomAD): Loss-of-function variants: 34 observed, 141.73 expected, observed/expected ratio (o/e) 0.24, 90% interval 0.18 to 0.32. The upper end of that interval is the gene's LOEUF score, 0.32, which puts it in group 1 of 6, group 1 being the genes least tolerant of losing a copy. Missense variants: 2,070 observed, 2,183 expected, observed/expected ratio (o/e) 0.95, 90% interval 0.91 to 0.98. Synonymous variants: 739 observed, 789.27 expected, observed/expected ratio (o/e) 0.94, 90% interval 0.88 to 1.
Homologues: Orthologues: chimpanzee AKAP11 (99% identical), macaque AKAP11 (95% identical), dog AKAP11 (82% identical), rabbit AKAP11 (80% identical), guinea pig AKAP11 (78% identical), pig AKAP11 (75% identical), rat Akap11 (74% identical), mouse Akap11 (74% identical), tropical clawed frog akap11 (45% identical), zebrafish akap11 (38% identical). Paralogues in human: SPHKAP (16% identical), AKAP4 (7% identical), AKAP3 (7% identical).
Diseases named in the same sentence as AKAP11 in open-access papers:
AKAP11 is named in the same sentence as 32 diseases in open-access papers, as found by Europe PMC text mining. Sharing a sentence is not in itself a finding about the gene and the disease. The quoted sentences say what the papers report.
bipolar disorder (9 papers, 2022 to 2025). A disorder of the brain that causes unusual shifts in mood, energy, activity levels and the ability to carry out day-to-day tasks. "Human genomic studies have identified protein-truncating variants in AKAP11 associated with both bipolar disorder (BD) and schizophrenia (SCZ), implicating a shared disease mechanism driven by loss-of-function." (PMID 40162211, 2025). "Recently, the largest whole-exome sequencing study of bipolar disorder conducted to date demonstrated a role for rare coding variations in the A-kinase anchoring protein-11 (AKAP11) as a significant risk factor in bipolar disorder aetiology." (PMID 37730845, 2023). "Akap11 LoF mutations are also associated with bipolar disorder." (PMID 41022686, 2025). "Furthermore, in the synaptic proteome of mutant mice with defective Akap11, a newly discovered common risk gene for schizophrenia and bipolar disorder, a similar dysregulation was observed in some of the same pathways." (PMID 41573035, 2025). "Furthermore, rare AKAP11 truncating variants were recently identified as significant risk factors for both bipolar disorder and schizophrenia from exome sequencing." (PMID 38600097, 2024). "These mouse EEG phenotypes reveal systems-level abnormalities caused by (even heterozygous) mutations in Grin2a and Akap11, and provide further justification, beyond their genetic validity, that these mouse mutants can serve as useful animal models of schizophrenia/bipolar disorder." (PMID 36914641, 2023). "Thus, AKAP11 is a shared risk gene for schizophrenia and bipolar disorder, underscoring the genetic overlap between these two disorders on the psychosis spectrum." (PMID 36914641, 2023). "In addition, AKAP11 is a bipolar disorder risk gene, recently identified as the top hit from Bipolar Exome (BipEx) sequencing studies of 13933 bipolar cases and 14422 controls." (PMID 36914641, 2023). "Mutations in AKAP11 promote schizophrenia and bipolar disorders (SZ-BP) through unknown mechanisms." (PMID 40263600, 2025). "Recently, polymorphisms in the AKAP11 gene sequence that lead to protein truncation and loss-of-function have been associated with increased risk for schizophrenia (SCZ) and bipolar disorder (BP)." (PMID 40263600, 2025). "AKAP11 and GRIN2A mutations are also associated with bipolar disorder, and epilepsy and developmental delay/intellectual disability, respectively." (PMID 36914641, 2023). "Besides their genetic validity, do Grin2a and Akap11 mutant mice have any neurobiological phenotype that resembles the human disease (schizophrenia and/or bipolar disorder)?" (PMID 36914641, 2023). "We found that Grin2a and Akap11 mutant mice possess several EEG features shared with human schizophrenia and bipolar disorder patients, including elevated gamma oscillations at rest, attenuated auditory steady-state responses (ASSR) at gamma frequencies, and changes in sleep spindle density." (PMID 36914641, 2023). "A major finding of our study is that Grin2a and Akap11 mutants show elevated gamma power during sleep and quiet wake, consistent with EEG findings in schizophrenia and to a lesser extent, bipolar disorder patients." (PMID 36914641, 2023). "The N1/MMN peak in the difference waveform is reported to be reduced on average in schizophrenia and bipolar disorder patients; however, we found no significant changes in Grin2a or Akap11 mutant mice, perhaps because of high variability in this metric." (PMID 36914641, 2023). "Biochemically, AKAP11 interacts with protein kinase A (PKA), a protein that is involved in a variety of biological processes including neuronal plasticity, and with glycogen synthase kinase 3 beta (GSK3β), one of the targets of lithium, a mainstay therapy for bipolar disorder." (PMID 36914641, 2023).
schizophrenia (7 papers, 2023 to 2025). A major psychotic disorder characterized by abnormalities in the perception or expression of reality. "We meta-analyzed large-scale brain transcriptomic data from mice harboring individual loss-of-function mutations in seven schizophrenia risk genes (Akap11, Dagla, Gria3, Grin2a, Sp4, Srrm2, Zmym2)." (PMID 41022686, 2025). "These shared EEG abnormalities suggest that Grin2a and Akap11 deficiencies impact, at least in part, the same brain networks and circuits that go awry in schizophrenia patients." (PMID 36914641, 2023). "The EEG phenotypes of Grin2a and Akap11 mutant mice show a variety of abnormal features that overlap considerably with human schizophrenia patients, reflecting systems-level changes caused by Grin2a and Akap11 deficiency." (PMID 36914641, 2023). "These neurophysiologic findings further substantiate Grin2a and Akap11 mutants as genetic models of schizophrenia and identify potential biomarkers for stratification of schizophrenia patients." (PMID 36914641, 2023). "Recent large-scale exome-sequencing efforts have uncovered rare genetic variants that confer a high risk for schizophrenia, including GRIN2A and AKAP11." (PMID 36914641, 2023). "Exome sequencing studies have uncovered rare, loss-of-function variants that greatly increase risk of schizophrenia, including loss-of-function mutations in GRIN2A (aka GluN2A or NR2A, encoding the NMDA receptor subunit 2A) and AKAP11 (A-Kinase Anchoring Protein 11)." (PMID 36914641, 2023). "By contrast, the non-DD/ID mutants (Akap11+/−, Dagla+/−, Gria3−/y, Sp4+/−) showed upregulation of these schizophrenia, NDD, and ASD gene sets in the thalamus." (PMID 41022686, 2025). "These and our findings further substantiate a link between schizophrenia and epilepsy, which is affected by GRIN2A, but not AKAP11 mutation." (PMID 36914641, 2023).
bladder cancer (2 papers, 2022 to 2025). "We found that GPM6B and AKAP11 showed low expression levels in bladder cancer tissue compared to the normal group, supported by RT-qPCR." (PMID 36003338, 2022). "We finally found that GPM6B and AKAP11 were down-regulated bladder cancer tissues compared to normal tissues using the GEPIA database, which was consistent with the results of RT-qPCR." (PMID 36003338, 2022). "We then investigated data for 19 pairs of patients with bladder cancer in The Cancer Genome Atlas database (TCGA) and found that expression levels of YTHDC1 and AKAP11 in bladder cancer tissue were downregulated in comparison with those in adjacent normal tissues." (PMID 40133252, 2025). "Thus, we predicted that lncRNA OCIAD1-AS1 might interact with miR-141-3p/miR-200a-3p to regulate GPM6B/AKAP11 to participate in mechanisms in bladder cancer." (PMID 36003338, 2022).
breast carcinoma (2 papers, 2018 to 2023). "Interestingly, AKAP5, AKAP9, AKAP11 and AKAP12 is expressed at lower levels in the basal-like and, less prominently in HER2-enriched subtypes, the breast cancer subtypes with highest risk of recurrence." (PMID 29433456, 2018).
autism (1 paper, 2023). Persistent deficits in social interaction and communication and interaction as well as a markedly restricted repertoire of activity and interest as well as repetitive patterns of behavior. "Two genes (SRRM2 and AKAP11) were newly implicated as SCZ risk genes, and one gene (PCLO) was identified as shared by individuals with SCZ and those with autism." (PMID 36914870, 2023).
endometrial cancer (1 paper, 2022). Primary or metastatic malignant neoplasm involving the endometrium (mucous membrane that lines the endometrial cavity). "The three LoF-intolerant genes (AKAP11, GRID1, and USP32) are all mutated in 5–8% of all Endometrial cancers in TCGA36." (PMID 35906355, 2022).
mental disorder (1 paper, 2025). A disease that has its basis in the disruption of mental process. "Finally, the DisGeNET annotation of the proteomics and phosphoproteomics data from Akap11-cKO neurons demonstrate a remarkable enrichment of psychiatric diseases including SCZ (top ranked), BD, and other mental disorders." (PMID 40162211, 2025).
cancer (2 papers, 2021 to 2022). A tumor composed of atypical neoplastic, often pleomorphic cells that invade other tissues. "This pattern could be linked to the under-expression of Akap11 in human induced pluripotent sensory neurons exposed to Bortezomib, an anti-cancer medication that induces painful peripheral neuropathy." (PMID 34680965, 2021). "In other words, miR-141-3p and miR-200a-3p were highly-expressed, but GPM6B and AKAP11 were low-expressed in cancer tissues." (PMID 36003338, 2022).
psychiatric diseases (2 papers, 2025). "Our current report offers a comprehensive view of AKAP11-regulated neuronal pathways and insight of the pathogenic mechanisms underlying the psychiatric diseases." (PMID 40162211, 2025). "Notably, AKAP11 deficiency impaired neurotransmission, providing key insights into the mechanism underlying AKAP11-associated psychiatric diseases." (PMID 40162211, 2025). "Given the genetic evidence linking AKAP-11-coding variants to the shared risk of BD and SCZ2,3,65, our studies shed a light on the molecular and cellular mechanisms underlying the psychiatric diseases." (PMID 40162211, 2025).
AKAP11 also shares sentences with these, for which no sentence is quoted: Intellectual disability (2 papers); neurodevelopmental disorder (2); Alzheimer disease (1); Crohn disease (1); developmental and epileptic encephalopathy (1); developmental delay (1); Dravet syndrome (1); epilepsy (1); gallbladder cancer (1); glioma (1); Hydroureter (1); inflammatory bone disease (1); kidney (1); Kidney Cyst (1); liver fibrosis (1); metastatic tumors (1); osteoporosis (1); periodontitis (1); peripheral neuropathy (1); polycystic kidney (1); Stroke (1); tumor (1); unipolar depression (1).